BRAF (B-Raf proto-oncogene, serine/threonine kinase)
Diseases named in the same sentence as BRAF in open-access papers (continued):
Sharing a sentence is not in itself a finding about the gene and the disease.
melanoma (continued). "Moreover, the inhibition of BRAF and MEK kinases by combined dabrafenib + trametinib treatment of BRAF-mutated melanoma led to the activation of the SEMA6A/RhoA/YAP pathway, which resulted in the remodeling of the cytoskeleton and a reduction in targeted therapy efficiency." (PMID 38067240, 2023). "However, the combination therapy exhibited less efficiency in melanoma patients without BRAF V600E mutation partly due to activating unoccupied CRAF protomer." (PMID 36872366, 2023). "However, in our study, all patients with BRAF mutant melanoma were treated with TTs as first‐line therapy, so our results cannot support this hypothesis." (PMID 38083908, 2023). "Interestingly, the combination of trametinib with the BRAFi PLX4720 induced ERK1/2 translocation to endoplasmic reticulum in BRAF mutant melanoma cells, and the protein kinase R-like endoplasmic reticulum kinase (PERK) phosphorylated ERK1/2 upon exiting endoplasmic reticulum." (PMID 37834284, 2023). "Although the association between TERT expression and the PFS could not be directly assessed in this small cohort, these results suggest that the high expression level of TERT might be involved in resistance to BRAF and MEK inhibitors in patients with BRAF-mutated melanomas." (PMID 37296851, 2023). "This approach is particularly relevant as BRAF-mutated PTCs and ATCs can be selectively targeted by BRAFi—i.e., vemurafenib and dabrafenib (combined with trametinib in ATC)—whose efficacy has been proven both in BRAFV600E-positive metastatic melanoma and in non-melanoma cancers." (PMID 37198319, 2023). "In addition, in vitro studies have shown that CDKN2A mutated melanomas may benefit from CDK4/6 inhibitors, and this therapy may be beneficial for patients with acquired resistance to BRAF/MEK inhibitors." (PMID 37373134, 2023). "However, it remains controversial whether immunotherapy or targeted therapy can be more optimal for BRAF‐mutant melanoma." (PMID 37016119, 2023). "From the US payer perspective, the vemurafenib-plus-cobimetinib strategy could be regarded as the most cost-effective treatment for patients with BRAF-mutant advanced melanoma when we set the WTP threshold at 150,000/QALY compared with the other 3 competing strategies." (PMID 36653848, 2023). "Our results demonstrate for the first time that a peripheral blood-derived biomarker (PD-L1+ PMN frequency) could independently predict patient clinical outcome to nivolumab in BRAF wild type melanoma patients, providing an additional tool for therapeutic choices in clinical oncology." (PMID 36016960, 2022). "Melanoma may arise from single melanocytes or clusters of melanocytes known as naevi, with or without BRAF or NRAS mutation." (PMID 35740696, 2022). "In some cancers where there is a mutant kinase driving the proliferation of the tumor cell by activating the MAPK pathway, such as mutant EGFR in NSCLC or BRAF(V600E) melanoma, vertical pathway combination kinase inhibitors maybe successful therapies in some patients." (PMID 34958800, 2022). "Analysis of melanoma patients who developed BRAF inhibitor resistance revealed increased mitogen-activated protein kinase signaling from either development of NRAS and KRAS mutations in progressive tumors, or through 2- to 15-fold increase in BRAF mRNA compared with patient-matched baseline tumors." (PMID 35525274, 2022). "Furthermore, upregulated miRNA signatures of miR-211-5p in melanoma and melanoma-derived vesicular secretome have been suggested as indicative of therapeutic resistance developed against BRAF inhibitors such as vemurafenib, used in treating metastatic melanomas." (PMID 35303879, 2022). "There were significant differences in subgroups of TNM stage, melanoma ulceration, pathologic stage, radiation therapy, gender, age, Breslow depth, BRAF status, indicating that STK17B expression level could impact the prognosis in SKCM patient with different pathological stages." (PMID 35171924, 2022).
melanoma (continued). "The use of small molecules to inhibit the proteins involved in re-sensitization of melanoma cells harboring mutant BRAF to BRAFi/MEKi would enable future application of new drug combinations that could enhance sensitivity and/or delay resistance to targeted therapy in metastatic melanoma." (PMID 36613518, 2022). "While trametinib looks promising for improving patient survival from BRAF mutant melanoma, a majority of patients with the NRAS mutation do not respond to MEKi-based therapy alone; only 28% of patients with NRAS-mutated melanoma achieve a stable disease with trametinib treatment." (PMID 35216449, 2022). "Thus, despite BRAF mutated tumors, which can be efficiently treated with combination ICI therapy and/or targeted approaches, little progress has been made in identifying effective therapeutic options for the treatment of patients with wild-type BRAF melanomas." (PMID 36016960, 2022). "Interestingly, our group demonstrated that stiffer collagen substrates resulted in increased in mechanosensing via YAP and myocardin-related transcription factor (MRTF) in MITFlow, dedifferentiated, invasive mesenchymal-like melanoma cells, in response to BRAF inhibitor treatment." (PMID 36119516, 2022). "Therefore, there is an urgent need to develop new BRAF‐mutant melanoma inhibitors." (PMID 35332658, 2022). "Additionally, the combination of BRAF and MEK inhibitors was reported to induce GSDME-dependent pyroptosis through caspase-3 and the release of pro-inflammatory factors in melanoma cells, which is associated with an increase in CD4+ T cell and CD8+ T cell infiltration and decreased TAM levels." (PMID 35990696, 2022). "Similarly, the phase III COLUMBUS trial illustrated benefits in terms of PFS and OS in the combination of encorafenib with binimetinib compared with vemurafenib when treating patients who were BRAF‐V600E mutant melanoma and were treatment naïve or progressed on or after first‐line immunotherapy." (PMID 36254250, 2022). "It is worthy of mentioning that the melanoma invasive state is mediated by key regulators, as AP1 and TEADs, and alterations in the expression of genes involved in invasion are also associated with an increase in patient's therapy resistance, including BRAF inhibitors." (PMID 35040264, 2022). "Moreover, lj‐2‐66 treatment significantly abrogated BRAF‐mutant melanoma cell colony formation." (PMID 35332658, 2022). "However, many driver mutations in melanoma (e.g., in the BRAF and NRAS oncogenes) do not fit this UV mutation signature." (PMID 36704334, 2022). "Melanomas were enriched in “naive T-cell”, “effector memory T-cell”, “exhausted T-cell”, “resting Treg T-cell” and “Th1-like” signatures, irrespective of their BRAF, NF1 or RAS mutational status." (PMID 36389735, 2022). "Moreover, it is important to note that, in addition to the classical signatures, atypical UV photoproducts can also be responsible for observed noncanonical oncogenic lesions, even at lower frequencies, in the most common melanoma driver genes, including BRAF and NRAS." (PMID 35804995, 2022). "V600E/K BRAF mutations result in activation of the RAS/RAF/mitogen-activated protein/extracellular signal-regulated kinase kinase (MEK)/extracellular-signal regulated kinases (ERK) pathway, leading to constitutive mitogen-activated protein kinase (MAPK) activity in melanoma." (PMID 35406541, 2022). "Interestingly, distinct hypermethylated genes have been found associated with genetic mutation subgroups, e.g., NF1 hypermethylation with NF1- and RAS-mutated melanomas, PTEN hypermethylation with BRAF-mutated, and CDK2A/B hypermethylation with BRAF-, RAS-, NF1-mutated and triple-WT melanomas." (PMID 35163453, 2022).
melanoma (continued). "Most importantly, if the pathologist overestimates the tumor burden and macrodissection is consequently left undone, the risk of false-negative results increases, which may leave a melanoma patient without the potential advantages of BRAF or MEK inhibitors." (PMID 36361209, 2022). "The results of this study suggest that BRAF mutational status alone does not predict the clinical outcomes in primary cutaneous melanoma and that the influence of miR-125b, miR-200c and miR-205 in the progression of melanoma is independent of BRAF mutations." (PMID 35326682, 2022). "Sequencing studies revealed genomic amplifications of mutant BRAF, expression of BRAF splicing variants or acquisition of mutations within MEK1 or MEK2 as frequent drivers of resistance to BRAF inhibition via the reactivation of the RAS pathway in melanoma patients." (PMID 35234863, 2022). "More related to diabetes, a study from 201229 found that metformin, an antidiabetic drug previously shown to have antitumor activity in several different cancers, did not affect BRAF‐mutated melanoma cells, but instead seemed to accelerate their growth in a xenograft mice model of melanoma." (PMID 35383926, 2022). "Compared with BRAF inhibitors alone, combining BRAF and MEK inhibitors have been demonstrated to enhance antitumor activity and delay the emergence of drug resistance in patients who have melanoma harboring BRAF V600E mutations, without increased overall toxicity." (PMID 35910024, 2022). "Investigation of novel therapeutic approaches involving combinations of several anti-melanoma agents (such as dual targeting of BRAF/MEK and cyclin-dependent kinases CDK4/6) could provide significant improvement in the prognosis of BRAF-mutated metastatic melanoma patients." (PMID 36613518, 2022). "BRAF mutation is highly prevalent in malignant melanoma, non-Hodgkin lymphoma, and other diseases." (PMID 36612173, 2022). "Interestingly, in melanoma, downregulation of MHC-I has been linked to the enrichment of a mesenchymal/invasive phenotypic profile in tumor cells, implying a coalescence of the mechanisms that confer resistance to both immunotherapy and BRAF inhibition." (PMID 35409020, 2022). "However, whether BRAF inhibitor resistant melanoma shows a similar pattern of increased FAK activity remains to be examined." (PMID 35525274, 2022). "Further subgroup analyses by PD-L1 and BRAF mutation status in other melanoma subtypes could not be conducted because of small sample sizes." (PMID 36304457, 2022). "Additionally, a triple wild-type melanoma has been described, being characterized by the lack of BRAF, RAS (N/H/K), and NF1 mutations." (PMID 35334544, 2022). "Therefore, Fra-1 inhibition might counteract the intrinsic or acquired melanoma resistance to BRAF and/or MEK inhibitors, by suppressing the ZEB1-regulated EMT-like transcriptional programs." (PMID 35326630, 2022). "Indeed, BRAF point mutations have been described in melanoma, non-Hodgkin’s lymphoma, CRC, papillary thyroid carcinoma, non-small-cell lung cancer, and gliomas." (PMID 35955671, 2022). "On the other hand, it is of note that rampant genetic changes in melanoma are capable of reducing apoptosis through the overexpression of B-cell lymphoma 2 (Bcl-2), loss of both Phosphatase and tensin homolog (PTEN) and nuclear factor-κB (NF-κB), and mutation of Akt3, NRAS, and BRAF." (PMID 36224606, 2022). "In addition, lj‐2‐66 suppressed the proliferation of BRAF inhibitor‐resistant (BRAFi‐resistant) melanoma cells independent of their resistance status, suggesting that lj‐2‐66 may be a potential drug for BRAF‐mutant melanoma treatment." (PMID 35332658, 2022). "Moreover, some apoptosis-related proteins have been associated with melanoma sensitivity to BRAF and MEK inhibitors, such as the Bcl2-interacting killer (BIK) protein that mediates on BRAF inhibitor effectiveness and Survivin that contributes to melanoma cells survival by inhibiting apoptosis." (PMID 36358912, 2022).
melanoma (continued). "Melanoma has been shown to metastasize to the brain in ~ 7% of all cases and up to 75% of those with stage IV disease regardless of whether the BRAF mutation is possessed." (PMID 35436952, 2022). "Preclinical studies showed that different sensitivity of BRAF V600E inhibition in melanoma and CRC may be due to the robust adaptive feedback signaling networks harbored in CRC, which leads to the reactivation of MAPK signaling following treatment with a BRAF inhibitor." (PMID 36556139, 2022). "In addition, we reviewed the literature on the performance of the BRAF Idylla test for melanoma." (PMID 35328303, 2022). "Non-CSD melanomas develop typically in younger patients and predominantly carry BRAF mutations, while CSD melanomas have a higher mutation burden, more often contain NF1, NRAS or KIT mutations and affect older people at the distal extremities and head and neck region." (PMID 35328746, 2022). "Our observation might lead to a conclusion that disrupted gene expression levels, including some splicing factors’ downregulation, in BRAF-driven melanoma cells can result in unbalanced splicing machinery that provides an advantage for cancer cells under a selective pressure of vemurafenib." (PMID 35883549, 2022). "CSD melanomas tend to arise in more elderly patients, with a history of multiple other non-melanoma skin cancers, a long history of accumulated sun exposure, and are more frequently driven by either gain of function NRAS mutations, loss of function NF1 mutations or BRAF gain of function mutations." (PMID 35884596, 2022). "In the plasma of melanoma patients harboring the BRAF V600E mutation, levels of lysophosphatidic acid, sphingomyelin, and long chain fatty acids were significantly increased in the cohort of patients that did not respond to BRAF inhibitor therapy." (PMID 35565240, 2022). "Interestingly, rearrangements and amplification of the MAP3K8 gene leading to increased levels of the truncated, active form of this protein are detected in approximately 15% of melanomas without driver mutations, such as BRAF, NRAS, or NF1." (PMID 35565444, 2022). "In this study, we established MM PDCs, which together with melanoma cell lines were applied to a functional drug testing platform covering 527 approved and investigational oncologic drugs to identify patient-specific treatment options for patients with BRAF wild-type MM." (PMID 34837846, 2022). "However, combinatorial BRAF/MEK inhibition has become the standard treatment for melanoma patients." (PMID 35525274, 2022). "In the early stage of melanoma, surgical resection is the first choice, while for advanced patients, traditional radiotherapy and chemotherapy showed very little effects for melanoma patients who cannot be surgically removed or who have metastasized and have BRAF V600E mutations." (PMID 36276290, 2022). "constructed a mutational subtype of melanoma based on the BRAF mutation patterns of 2 FAM-related genes, ALDH1A1 and ALDH1A3; however, this CM subtype accounts for ALDH1A3 expression as only a prognostic marker for BRAF/MEK inhibitor treatment response in BRAF-mutant metastatic melanoma patients." (PMID 36466837, 2022). "The influence of BRAF mutation on the survival of patients with melanoma is not clearly defined." (PMID 35406444, 2022). "Notably, the efficacy of a BRAF-MEK inhibitor in eliminating melanoma is completely blocked in immunodeficient GSDME-positive mice, implying that the potential molecular mechanism of BRAF-MEK inhibitor treatment of melanoma is a GSDEM-dependent antitumour immune response." (PMID 35896522, 2022). "Thus, metabolic rewiring is such an important process that melanoma cells usually show enhanced activity of general metabolic effectors such as BRAF and NRAS, which activate the downstream MAPK pathway, or the loss of PTEN and activation of the PI3K/AKT pathway, to increase their metabolic capacity." (PMID 35912100, 2022).
melanoma (continued). "It is still unknown if the mutation in BRAF is implicated in the transformation of benign nevi into malignant melanoma or not.The presence of a BRAF mutation predicts a poor outcome in advanced-stage melanoma patients." (PMID 35326682, 2022). "Therefore, it investigates why BRAF would be transformed higher commonly than NRAS in melanoma." (PMID 36551688, 2022). "Furthermore, the anti‐BRAF‐mutant melanoma effect and mechanism of this compound were explored." (PMID 35332658, 2022). "Hence, we can conclude from these data that the circulating levels of the oncosuppressor miR-579-3p and of the oncomiR miR-4488 are able to identify BRAF-mutated melanoma patients who benefit or not from target therapy with BRAF and MEK inhibitors." (PMID 36438490, 2022). "In addition, BH4 increased the WM1552C melanoma cell sensitivity to vemurafenib (BRAF inhibitor)." (PMID 35682659, 2022). "Notably, melanoma metabolism has been intensively studied, and its metabolic signaling pathways have been shown to be involved in cancer cell survival, invasion, metastasis, and resistance to BRAF inhibitor therapy or PD-1 blockade immunotherapy." (PMID 35408839, 2022). "Meta-analysis of 5 randomized controlled trials including 2,317 patients with melanoma concluded that combination therapy with BRAF inhibitor and MEK inhibitor was associated with a higher risk of pulmonary embolism (RR: 4.36; 95% CI: 1.23-15.45; P = 0.02) compared with BRAF inhibitor monotherapy." (PMID 35492830, 2022). "Therefore, we treated a panel of melanoma cell lines that included the two main driving mutations in melanoma, BRAFV600E (A375, SK-Mel28, and WM-793 cells) and the NRASQ61R (SK-Mel2 cells) point mutations with the BRAF inhibitor PLX4032 (vemurafenib) for 1 or 24 h." (PMID 36038253, 2022). "Therefore, BRAF/MEK inhibitors have been developed to treat patients with BRAF-mutant melanoma." (PMID 36588679, 2022). "Although demonstrating better clinical efficacy than conventional chemotherapies, these BRAF and MEK inhibitors engender inevitable drug resistance caused by complex mechanisms, which eventually lead to tumor cell proliferation and poor prognosis of melanoma patients." (PMID 36003368, 2022). "Indeed, ICI is currently positioned as a first-line therapy for melanoma without BRAF mutations, and the 3-year overall survival rates have reached 51%, 40% and 56%, respectively." (PMID 35954389, 2022). "Therefore, Polish and European guidelines recommend that combination as a preferred first-line treatment in advanced melanoma regardless of BRAF mutation status and especially in patients previously exposed to immunotherapy in the adjuvant setting." (PMID 36289790, 2022). "Unlike other oncogenic addicted tumors, namely EGFR driven lung cancer (NSCLC), where the appearance of secondary mutation in the target gene (EGFR) is a common mechanism of resistance to EGFR inhibitors, no BRAF secondary mutation has been so far reported in BRAFi‐resistant melanomas." (PMID 36305167, 2022). "Moreover, mutations in the telomerase reverse transcriptase are more common in sun-exposed melanoma than in non-exposed melanoma, and they tend to co-occur with other common melanoma mutations such as BRAF and CDKN2A (Cyclin Dependent Kinase Inhibitor 2A)." (PMID 36365208, 2022). "However, we observed significantly fewer structural variations overall in melanomas with BRAF class 1 mutations compared to those without (136 vs. 234 junctions on average; P = 0.0015), which remains significant after accounting for tumor purity and ploidy." (PMID 35706047, 2022). "However, in xenograft melanoma models, trametinib was more effective in BRAF-mutant tumors." (PMID 36358912, 2022). "Thus, our analysis suggests, albeit preliminarily, that PC-mediated anaplerosis may play a key role in the response of melanoma cells to treatment with BRAF signaling inhibitors, at least at short time scales." (PMID 35148308, 2022).